SOX2 (SRY-box transcription factor 2)
Diseases named in the same sentence as SOX2 in open-access papers (continued):
Sharing a sentence is not in itself a finding about the gene and the disease.
cancer (continued). "Abnormal SOX2 expression has been found in different cancers and is correlated with the presence of CSCs." (PMID 33489519, 2020). "SOX2 overexpression is thought of as a major contributor in maintaining the antiapoptotic and tumorigenic properties of cancer stem cells." (PMID 32098209, 2020). "Many upregulated genes such as cancer stem cell marker (SOX2/9), hypoxia inducible factor (HIF1α), TGF-β signaling associated receptor (TGFBR2), and differentiation related transcription factor (RUNX2) were reported to promote tamoxifen resistance." (PMID 32420379, 2020). "Unfortunately, the “undruggable” characteristics of transcription factors such as SOX2 has largely constrained the clinical potential of SOX2-centered therapeutic strategies in major cancer types." (PMID 32191225, 2020). "It was reported that SOX2 plays a pivotal role in oncogenesis and progression of multiple cancers including HCC." (PMID 33112555, 2020). "Other studies suggest that SOX2 is critically involved, at least in part, in cancer initiation and progression via modulation of CSC stemness." (PMID 32483269, 2020). "Several investigators have found that NOTCH1 expression and activation correlate with the expression of cancer stem cell markers, including SOX2 and aldehyde dehydrogenase (ALDH) activity measured by the ALDEFLUOR assay." (PMID 33322834, 2020). "SOX2 was the most upregulated TF in cancer stem cells from skin squamous cell carcinoma (SCC) and was shown to control self-renewal." (PMID 33202305, 2020). "A little has been known about how SOX2 promoter is turned on upon exposures to anti-cancer therapies." (PMID 30517668, 2020). "MUC1 and MUC4 induced by IL-17RB upregulate expression of cancer stemness-related genes, such as SOX2, Nanog, Oct-4, and surface CD44 to facilitate sphere formation." (PMID 33082357, 2020). "Although SOX2 is highly relevant to cancer initiation, progression and development of drug resistance, directly targeting SOX2 has been proved to be difficult, since SOX2 is an “undrugable” transcription factor." (PMID 31748974, 2020). "Typically, SOX2 is involved in major mechanisms ascribed to the phenomena of therapeutic resistances in cancers, which ultimately lead to clinical relapse." (PMID 30517668, 2020). "The unfavorable prognostic effect of Sox2 was complementary to the favorable effects of AR, and independent from cancer stage at diagnosis." (PMID 33553286, 2020). "IL-22 activates the STAT3 phosphorylation cascade in cancer cells and induces the expression of stem cell markers (SOX2, NANOG, and POU5F1), resulting in increased cancer stemness and tumorigenic potential." (PMID 32670290, 2020). "With respect to the effect of aspirin on cancer cell stemness properties, we found that the immunocytochemical staining of SOX2 and OCT4 stemness markers decreases in the cisplatin/aspirin-treated groups versus DMSO controls." (PMID 32854760, 2020). "We therefore propose that, downstream of FGFR signaling, AKT regulates cancer stemness via impacting SOX2 ubiquitination and subcellular localization." (PMID 32457900, 2020). "It is noteworthy that EMT induction enhances viability via the stimulation of cancer stem cell markers such as Bmi1 and Sox2." (PMID 32752069, 2020). "Analysis of TCGA (the Cancer Genome Atlas) datasets suggested that the level of LINC00963 was positively correlated with the expression of the cancer stemness markers (Sox2 and CD44) and drug resistance markers (ABCG2 and ABCB5)." (PMID 32357409, 2020). "Amidst the core regulators of stemness (e.g. OCT4, SOX2, and NANOG), SOX2 expression has been identified in myriad diversities of cancers with poor disease prognosis." (PMID 30517668, 2020). "Here we identified that metastatic phosphatase of regenerating liver 3 (PRL-3) transcriptionally upregulates SOX2 in the expansion of CSC sub-population from normal cancer cells." (PMID 31887658, 2020).
cancer (continued). "With this knowledge, the exosome-mediated delivery of SOX2 DNA, its subsequent internalization, and processing by the recipient cell need to be investigated, especially for the normal cells receiving cancer-derived exosomes." (PMID 32092088, 2020). "SOX2 is known to be misregulated in cancer cells by changes in miRNA function, such as SNPs in the binding sites." (PMID 32092088, 2020). "Next, we examined if PBI-05204 affects the expression of stem cell markers including SOX2, a well-known stem cell transcription factor in cancer stem cells including GSCs." (PMID 33013390, 2020). "Our findings highlight the crucial relationship between CAFs and PCAT-1 which establish a CD133/SOX2-related stem cell phenotype and promote cancer cell chemoresistance." (PMID 32754302, 2020). "Our results showed that interfering with SOX2 expression in SOX2-expressing cells significantly reduces their cancer stemness." (PMID 32457900, 2020). "The expression levels and mechanisms of SOX2/9 proteins are highly correlated with their role in the cell cycle and the proliferation of cancer cells." (PMID 33152990, 2020). "A migrative, invasive and metastatic characteristic of tumors is the epithelial–mesenchymal transition (EMT), and SOX2 is well known to promote EMT in various cancers." (PMID 33182283, 2020). "SOX2 is overexpressed in CRC91 and its expression associates with a cancer stem cell state and downregulation of the intestinal epithelial marker CDX292." (PMID 32737302, 2020). "Significantly, recent studies have determined that the function of SOX2 in cancer cells is highly dose dependent." (PMID 32998722, 2020). "The probabilities of cancer progression at 1 year post diagnosis were 46% and 57% in the Sox2– and Sox2+ groups, respectively." (PMID 33553286, 2020). "It is noteworthy that CD133+ GBM’s exosomal SOX2 PCR product had additional SNPs besides the ones reported in connection to cancers mentioned in the result section." (PMID 32092088, 2020). "The transcription factor SOX2 has been identified as one of the core regulators that maintain the self‐renewal of embryonic and cancer stem cells." (PMID 31823521, 2020). "Metastatic cancer stem cells in SH-SY5Y cell line also have increased levels of SOX2 as compared to their parent cells." (PMID 32092088, 2020). "Increased Sox2 expression has been found in different types of cancer, including breast, colorectal, or lung, among others." (PMID 32290242, 2020). "Studies have revealed that SOX2 is an oncogene known to be amplified and overexpressed in carcinogenesis, metastasis and recurrence in many cancer types." (PMID 33153498, 2020). "These authors revealed that expression of tenascin-C in ESCC cells is directly associated with that of SRY-box transcription factor 2 (SOX2), a well-known cancer stem cell marker." (PMID 32079295, 2020). "Recently, SOX2 amplification, usually couples with aberrantly increased expression, were found in various human cancers, including breast, lung, esophagus, colon, prostate, ovarian among the others." (PMID 31748974, 2020). "IHC performed for SOX2 in no-ADT specimens exhibited a mixed basal and luminal epithelial cell staining in cancer with higher percentage of SOX2 positive cells, specifically in basal cells." (PMID 33339129, 2020). "To identify the relevance of SOX2 to cancer stemness, we engineered two stable cell lines designated as Sh-SOX2-1 and Sh-SOX2-2, which display a knockdown of SOX2 and Sh-scramble control." (PMID 32457900, 2020). "This would raise the possibility of pharmacologically managing, in the appropriate direction and intensity, the physiological versus pathological processes of SOX2-related reparative cellular reprogramming in aging and cancer." (PMID 32191225, 2020). "With respect to the effect of aspirin on cancer cell stemness properties, we found that the immunocytochemical staining of SOX2 and OCT4 stemness markers decreases in the aspirin-treated groups versus DMSO controls." (PMID 32854760, 2020).
cancer (continued). "Although the molecular definition of CSCs in HCC is still emerging such as CD24, CD44, CD90 and EPCAM7,8, three transcription factors, Oct4, Nanog and Sox2, have been strongly identified as master regulators of cancer stemness." (PMID 32024815, 2020). "We recently found that neddylation inhibitor MLN4924 effectively blocks SOX2 expression in many types of human cancer cells by targeting the FBXW2–MSX2–SOX2 axis." (PMID 32728033, 2020). "In many types of human cancer, SOX2 is dysregulated due to gene amplification and protein overexpression." (PMID 32728033, 2020). "It has been revealed that SOX2 is overexpressed in many cancer stem progenitor cells and is involved in chemotherapy resistance and the metastasis and recurrence of cancer." (PMID 33153498, 2020). "In this review, we first briefly introduced SOX2 as a transcription factor, its domain structure, normal physiological functions, and its involvement in human cancers." (PMID 32728033, 2020). "It has been suggested that SOX2-silenced cancer cells have the potential to escape cell-cycle arrest and become resistant to apoptosis, thereby enhancing carcinogenesis." (PMID 32098209, 2020). "With respect to the effect of ibuprofen on cancer cell stemness properties, we found that the immunocytochemical staining of SOX2 and OCT4 stemness markers decreases in the ibuprofen-treated groups versus DMSO controls." (PMID 32528119, 2020). "Given the crucial role of PM2.5 and exercise in DNA methylation and cancer, we conducted this study to assess the association of exercise and PM2.5 with SOX2-promoter methylation in Taiwanese adults aged 30–70 years." (PMID 32098209, 2020). "Despite the marked expression of SOX2 in cancer, this protein is also expressed in the epithelium of developing teeth, in the surface epithelium of oral mucosa and in the epithelium lining of dentigerous cysts." (PMID 31967981, 2020). "The stem cell transcription factor SOX2 plays prominent roles during mammalian development, cellular reprogramming, and cancer progression." (PMID 32998722, 2020). "We then analyzed by RT-qPCR the expression of the different markers involved in the cancer stem cells’ biology (Sox2, Oct3/4, Notch1, Nanog, Abcg2, Aldh1a1 and Aldh1a3)." (PMID 32610610, 2020). "By reduction of MSI1 expression in spheroid culture, proliferation of cancer stem cells decreases through reduction of Notch1 and cancer stem cell markers such as Oct4, Sox2, and c-Myc." (PMID 32448364, 2020). "There are numerous cancer stemness markers proposed in previous studies including pluripotency markers Oct-4, Nanog, and SOX2, which are considered as poor prognosis indicators of CRC." (PMID 31963305, 2020). "Our study suggests that EGFR plays an important role in the development of cancer stem cells by stabilizing SOX2." (PMID 31823521, 2020). "In cancer cells, SOX2 is involved in regulation of cellular proliferation, signalling in apoptosis, invasion, and migration." (PMID 33489519, 2020). "We also labeled tumorspheres for Sox2 (a marker for cancer stem cells), Arl13b, and pericentrin to determine if cilia are present on cancer stem cells." (PMID 32811879, 2020). "Research of the past view years expanded our understanding of the various physiological functions the cell-fate determining transcription factor SOX2 exerts in ontogenesis, reprogramming, and cancer." (PMID 31477842, 2020). "SOX2 has been reported to act as an oncogene during cancer progression and is frequently overexpressed in poorly differentiated CRC28." (PMID 32144236, 2020). "The potential of QOS for gene expression analysis were validated with the tracing of two genes that are markers of cancer stem cells, namely Oct-4 and SOX-2." (PMID 32111825, 2020). "Mechanistically, SOX2 promotes proliferation, survival, invasion/metastasis, cancer stemness, and drug resistance." (PMID 32728033, 2020). "SOX2 has been shown to be expressed in at least 25 different types of cancer and to drive cancer cell survival." (PMID 33233861, 2020).
cancer (continued). "SOX2 has a crucial role in the proliferation of cancer Cells through c-MYC in Wnt/β-catenin pathway." (PMID 33033513, 2020). "Sox2-positive FMCs were much more likely to kill feline patients than Sox2-negative carcinomas (HR = 1.57, 95% CI 1.10–2.25, p = 0.0093)." (PMID 33553286, 2020). "The accumulated FOXO1 promotes transcriptional expression of SOX2, a transcriptional factor for cancer stemness, which in turn, activates FOXO1 transcription and forms a positive regulatory loop." (PMID 31844113, 2019). "The CT26Flag−CAGE1 and CT26Flag−CAGE2 cells showed higher expression of CD133 and SOX2, markers of cancer stemness, than CT26." (PMID 31799196, 2019). "SOX2 can enhance translation of oncogenic proteins driven by key cancer transcription factors, including NFE2L2, while signaling from PIK3CA can maintain NFE2L2 protein levels." (PMID 31395880, 2019). "SOX2, defined as a main stemness marker, is upregulated in cancer stem cells, and it has the capability to produce the diversity of cell types." (PMID 31516388, 2019). "CSCs, depended on cancer types, occupied different markers, such as, SOX2, CD133, epithelial cell adhesion molecule (EpCAM), CD166, CD24, CD29, Lgr5, Kruppel-like factor 4 (Klf4) and ALDH." (PMID 30962766, 2019). "Although molecular markers of cancer stemness are still emerging, transcription factors including Nanog, Sox2 and Oct4 have been strongly identified as master mediators of pluripotency." (PMID 30999932, 2019). "Down-regulation of SOX2 significantly reduced the IC50 of gemcitabine in the resistant cancer cells." (PMID 30382189, 2019). "CD133 and CD44 are two stem cell markers, while SOX2 and Nanog are two transcription factors involved in the maintenance of cancer stem-like cell properties." (PMID 31130822, 2019). "In this study, we confirm that clinical expression of pluripotent factors OCT4, SOX2 and NANOG is associated with treatment resistance and lethal cancers." (PMID 30742096, 2019). "SOX2 has been studied in some types of human cancers and facilitates tumor initiation and progression." (PMID 30693028, 2019). "The strong correlation between Sox2 and ST6Gal-I expression is likely due, at least in part, to the coordinate amplification of these two genes in cancer cells." (PMID 31610800, 2019). "It is noteworthy that both NEDD9 and SOX2 are recognized as HIF-1α downstream genes where they also participate in the control of cancer cell migration." (PMID 31462898, 2019). "Recently, it was established that SOX2 can also increase the expression of podoplanin in cancer stem cells." (PMID 31508790, 2019). "Pathologically, SOX2 also shows higher expression in gastric, pancreatic, breast and other malignant tumors." (PMID 31462898, 2019). "Mechanistically, Sox9 acts downstream of Sox2 to control luminal progenitor cell content and is required for expression of the cancer stem cell marker ALDH1A3 and Wnt signalling activity." (PMID 30622340, 2019). "RNA expression of TOP2A, PCNA, SOX2, EZH2, ZEB1 genes associated with cell cycle, cancer cell ‘stemness’, and FOXM1‐FOXO activities was similarly affected in both cases." (PMID 30927552, 2019). "SOX2 is aberrantly expressed in several types of cancers, such as breast, lung, ovarian and prostate cancers." (PMID 31844113, 2019). "SOX2 (sex-determining region Y (SRY)-box2) has a role in the maintenance of cancer stem cells (CSCs)." (PMID 31416295, 2019). "Silencing HMGB1 in irradiated cancer cells (feeder cells) attenuated expression levels of stem cell-related markers (Oct4, Sox2, C-myc, and Nanog) and sphere forming ability of CD133− reporter cells." (PMID 31558702, 2019). "Stemness in normal as well as cancer stem cells is maintained by a list of transcription factors such as, Nanog, c-Myc, Oct-4 and Sox-2." (PMID 30728896, 2019). "EMT is also a critical regulator in the progression of cancer metastasis in BCC through SOX2 expression that regulates the EMT processes and proliferation of BCC cells." (PMID 31934531, 2019).
cancer (continued). "Collectively, our findings underscore a novel role of CD44 signaling in the maintenance of stemness and progression of cancer through SOX2 in AR‐independent PC3 cells." (PMID 30206982, 2019). "Transcription factors (including Oct4, Sox2, Nanog, and c-Myc) are known to play crucial roles in maintaining the stemness and self-renewal abilities of cancer stem cells." (PMID 31558702, 2019). "In fact, PI3K and AKT inhibitors, in several preclinical studies, were demonstrated to be able to reduce SOX2-driven growth, viability, migration, tumorigenicity, and drug resistance of cancer cells." (PMID 31850198, 2019). "In this way, Sox2+ MB cancer cells are similar to other cancer stem cells and NSCs of the cerebellar ventricular zone, which proliferate in response to Wnt signaling." (PMID 31700613, 2019). "We also showed that MTA3 was capable of repressing cancer cell proliferation through inhibiting SOX2 expression." (PMID 31552166, 2019). "Both genes are commonly amplified in cancer cells due to their shared presence within the 3q26 amplicon, and then the transcribed Sox2 protein binds the ST6GAL1 promoter to further enhance ST6Gal-I expression." (PMID 31610800, 2019). "To identify the downstream modulator of TARBP2, we determined the expression of several key factors that have been reported to modulate self-renewal and drug resistance of cancer cells, including SOX2, Nanog, OCT4, Lin28A, CCND1." (PMID 30759864, 2019). "We have also delineated an indispensable role for the stem cell transcription factor SOX2 in CDK1-mediated stemness and tumorigenesis by demonstrating the interaction of CDK1 with SOX2 in cancer cells." (PMID 31080551, 2019). "SOX2 has been reported to play an important role not only in development and somatic reprogramming but also in cancer initiation/progression." (PMID 31041783, 2019). "It is known that sex-determining region Y-box 2 (Sox2) is of vital importance in regulation of stem cells in embryos and in cancer." (PMID 30382189, 2019). "As an embryonic transcription factor, SOX2 maintains cancer stem cells and drives the epithelial-to-mesenchymal transition (EMT)." (PMID 30988674, 2019). "In this study, we used murine induced pluripotent stem cells that expressed specific stem cell genes such as Nanog, Oct3/4, Sox2, Klf4, and c-Myc, and two human cancer cell lines with similar stem cell gene expression." (PMID 30717462, 2019). "Consequently, SOX2 could be a potentially useful predictor of cancer risk in the oral cavity." (PMID 31640140, 2019). "Some studies showed that overexpression of SOX2 promotes human cancer cell proliferation mainly through promoting migration and invasion via PI3K/AKT by increasing MMP2 expression." (PMID 31934531, 2019). "Because Bergmann glia express Sox2, this cell type is a potential source of Sox2+ MB cancer-propagating cells." (PMID 31700613, 2019). "Previously we showed that the development of tamoxifen resistance is driven by Sox2-dependent activation of Wnt signalling in cancer stem/progenitor cells." (PMID 30622340, 2019). "The expression levels of cancer stemness-related genes, namely, Sox2, Oct4 and Nanog, were examined." (PMID 31455383, 2019). "In HNSCC, SOX2 expression has been found to induce cancer stem cell (CSC)-like properties, including increased self-renewal, tumorigenic potential and chemoresistence." (PMID 30823625, 2019). "Further, oleacein fully suppressed the expression of the transcription factor SOX2 (SEX determining Region Y-box 2) in cancer stem-like and induced pluripotent stem (iPS) cells, which specifically occurs under the control of an LSD1-targeted distal enhancer." (PMID 31331073, 2019). "For example, ASCL1, CDX2, IRF4, MITF, NKX2-1, PAX8 and SOX2 were pinpointed as outliers in cell lines of their corresponding cancer tissue origins." (PMID 31050342, 2019).